MSLN (mesothelin)
Diseases named in the same sentence as MSLN in open-access papers (continued):
Sharing a sentence is not in itself a finding about the gene and the disease.
ovarian carcinoma (continued). "Additionally, BBζ-Neo also effectively impeded the tumor growth and improved the survival of mice bearing xenograft tumors derived from MSLN-positive, Caov-3 human ovarian cancer cells." (PMID 40025022, 2025). "Furthermore, mesothelin plays an important role in cell adhesion, drug resistance, and tumor metastasis, which makes it a potential therapeutic target for ovarian cancer." (PMID 40417700, 2025). "Mesothelin (MSLN) is among the most studied cancer-related antigens, and it is extensively studied as a therapeutic target for the treatment of various malignancies, including pleural mesothelioma, pancreatic ductal adenocarcinoma, and ovarian cancer." (PMID 41335396, 2025). "This study evaluates anti-MSLN CAR-T therapy for ovarian cancer." (PMID 40849468, 2025). "Elucidating the relationship between the expression pattern of MSLN in ovarian cancer and clinical prognosis could help enhance its value in clinical practice." (PMID 41400642, 2025). "For example, by simultaneously targeting the FOLR1 and MSLN antigens, which are highly expressed in ovarian cancer, tumor cell elimination significantly increased from 48% with single-target therapy to 88.75%, effectively reducing the risk of recurrence caused by antigen loss." (PMID 41400642, 2025). "Interestingly, a clinical study conducted in patients with MSLN-positive drug-resistant, relapsed ovarian cancer showed differences in metabolic profiles between patients with high or low response to an anti-MSLN CAR-T therapy (known as LD013) (NCT05372692)." (PMID 41335396, 2025). "To confirm that the cytotoxic impact of MSLN-CAR T cells on ovarian cancer cells was dependent on MUC16 expression, we asked if forced expression of MUC16 in SKOV3 cells could lead to their cytotoxic killing." (PMID 38637885, 2024). "Moreover, MSLN’s impact on the ovarian cancer microenvironment was known to be involved in cell survival, proliferation, tumor progression, and adherence." (PMID 38918474, 2024). "Altogether, our study shows that treosulfan and fludarabine can mediate cytotoxicity toward SKOV3 and OVCAR4 ovarian cancer cell lines without inducing loss of MSLN cell surface expression or having a negative impact on MSLN-CAR T cells." (PMID 38954005, 2024). "A phase I clinical trial using intravenous SynKIR-110 is registered in the United States (NCT05568680) for patients with mesothelin-expressing ovarian cancer, mesothelioma, and cholangiocarcinoma, though the status is currently unknown." (PMID 38667465, 2024). "Interestingly, Mesothelin was described to be correlated with chemo-resistance in ovarian cancer, and increased Mesothelin expression was detected in chemoresistant patients." (PMID 39781381, 2024). "Thus, our MSLN-CAR T cell approach shows specificity for MUC16 overexpression in ovarian cancer cells that drives their effective killing in vitro." (PMID 38637885, 2024). "Furthermore, we found that MSLN-CAR T cells were effective to shrink tumors from ovarian cancer cell in immunocompromised mice." (PMID 38637885, 2024). "On this basis, ovarian cancer cell lines with high MSLN expression are resistant to anoikis." (PMID 39023820, 2024). "Currently, there is an ongoing phase I clinical trial evaluating the oncovirus VCN-1 administered in combination with human CAR-T cells targeting mesothelin in patients with unresectable or metastatic pancreatic or persistent or recurrent ovarian cancer (NCT05057715)." (PMID 38667465, 2024). "Particularly, high expression of MSLN is observed in 60%–65% ovarian cancer." (PMID 39136096, 2024). "Thus, the specificity of MSLN-CAR T cells for ovarian cancer cells is related to such cells expressing high levels of MUC16." (PMID 38637885, 2024). "Like MUC16, MSLN is over-expressed in ovarian cancer with limited expression in normal tissues." (PMID 40836974, 2024).
ovarian carcinoma (continued). "Mesothelin (MSLN) is a cancer‐associated antigen and a promising target for personalised therapies in diseases that overexpress MSLN, such as mesothelioma, pancreatic and ovarian cancer." (PMID 37040900, 2023). "MSLN is highly expressed on a variety of tumours, including ovarian cancer." (PMID 36166071, 2023). "It has been suggested that the determination of mesothelin simultaneously with other markers could increase the sensitivity of detecting ovarian cancer at early stages." (PMID 37238197, 2023). "Mesothelin is a tumor-associated antigen found highly expressed in various cancer types, including malignant pleural mesotheliomas (MPM), pancreatic cancers, and ovarian cancers." (PMID 37958672, 2023). "T cells expressing a mesothelin (MSLN)-specific T cell receptor fusion construct (TRuC®), called TC-210, have demonstrated robust antitumor activity in preclinical models of mesothelioma, ovarian cancer, and lung cancer." (PMID 37848682, 2023). "They confirmed MSLN overexpression in chemoresistant ovarian cancer cell lines." (PMID 37238197, 2023). "However, it has been found that MSLN is overexpressed in a variety of cancers, including malignant mesothelioma, ovarian cancer, breast cancer, pancreatic cancer, lung cancer, gastric cancer, cervical cancer, uterine serous cancer and cholangiocarcinoma." (PMID 36900151, 2023). "In this study, we designed a new type of chimeric receptor T cell targeting CA125, based on the natural binding of mesothelin to CA125 in patients with ovarian cancer, to reverse the role of this ligand-receptor binding activity in promoting tumor transformation." (PMID 37670338, 2023). "Due to the heterogenous expression of MSLN in ovarian cancer, we hypothesized that MSLN-targeting CAR (MCAR)-engineered Vδ2 T cells may exhibit superior antitumor activity due to the potential of multiple targeting capability." (PMID 37938576, 2023). "The results of one such clinical trial targeting MSLN in ovarian cancer have been published." (PMID 36166071, 2023). "Mesothelin, a differentiation antigen, is highly expressed in ovarian cancer, which could induce humoral immune response in ovarian cancer patients." (PMID 37597098, 2023). "Although the MSLN protein is expressed at low levels in HMs, it is overexpressed in asbestos-exposed subjects and aberrantly expressed in several solid tumors, including gastric, lung, pancreatic, and ovarian cancers as well as in mesothelioma." (PMID 37901248, 2023). "For instance, in the context of ovarian cancer, certain malignant cells might be proficient in the expression of mesothelin, MISIIR, and EpCAM, whereas there might be tumor cells within a given tumor site that express neither." (PMID 38146364, 2023). "Since cancer stem cells (CSCs) contribute to pathogenesis, chemoresistance and malignant behavior in ovarian cancer (OC), we hypothesized that MSLN expression could be creating a favorable environment that nurtures CSCs." (PMID 35162954, 2022). "Therefore, a systematic bioinformatics analysis of MSLN-related issues in ovarian cancer can give us more insights into the study." (PMID 35692779, 2022). "Our research suggests that MSLN participates in a variety of pathways related to the suppression of immune activation and promotion of chemoresistance, leading to a poor prognosis in ovarian cancer." (PMID 35692779, 2022). "However, recent studies have shown that more than 70% of cancer patients express mesothelin in their tissues, including colorectal cancer, lung cancer, stomach cancer, mesothelioma, ovarian cancer, and pancreatic cancer." (PMID 35340746, 2022). "Mesothelin (encoded by the MSLN gene) involves in cell adhesion and cell-matrix adhesion as membrane-anchored forms, which is also a target of CAR-T cells for treating gastric cancer and ovarian cancer triple-negative breast cancer." (PMID 35993054, 2022).
ovarian carcinoma (continued). "However, the mechanism of MSLN in ovarian cancer and immune-related bioinformatics analysis research was very limited." (PMID 35692779, 2022). "Mesothelin (MSLN), a 40-kDa glycoprotein found in normal mesothelial cells, seems to be overexpressed in about 30% of all cancers, including in mesothelioma, ovarian cancer, pancreatic cancer, and other solid tumors." (PMID 35883451, 2022). "However, the expression of MSLN is dysregulated in many types of tumors including mesothelioma, pancreatic cancer, ovarian cancer, etc.." (PMID 35692779, 2022). "Interestingly, both M28z and MBBz CAR T cells acquired the MSLN antigen through trogocytosis from ovarian cancer cells which, in turn, lost MSLN surface expression." (PMID 35898704, 2022). "However, CA125 can also be found on the surface of ovarian cancer cells and acts as an adhesion molecule, binding to mesothelin on the mesothelial cell surface." (PMID 35574025, 2022). "Therefore, the present study clarifies the gene expression level of MSLN in ovarian cancer, prognostic influence, related protein analysis, and immune correlation analysis." (PMID 35692779, 2022). "In animal models, antibodies to mesothelin block ovarian carcinoma seeding to the peritoneum." (PMID 36497364, 2022). "Through their experiment in patient-derived xenograft studies, the authors proved that the binding of CA125 with mesothelin promotes the metastasis of ovarian cancer, and they hypothesised a cascade of molecular events involving many different molecules." (PMID 35565412, 2022). "The expression of MSLN in healthy tissues is restricted to the mesothelial cells of the pericardium, peritoneum and pleura, while it is found in various malignancies apart from PaC, including ovarian cancer or mesothelioma." (PMID 36009489, 2022). "Mesothelin (MSLN) is a membrane-bound glycoprotein overexpressed in more than 80–100% of pancreatic and ovarian cancer with an unknown specific role in tumor progression." (PMID 35836956, 2022). "A human ovarian cancer cell line OVCAR3-FG overexpressing MSLN and Fluc-GFP was used as a target." (PMID 35681730, 2022). "Therefore, it worth further investigation about MSLN in the field of immunotherapy in ovarian cancer." (PMID 35692779, 2022). "In ovarian carcinomas, it has been demonstrated that the binding of MSLN with its partner MUC16 (CA125) may play a role in cell adhesion, facilitating intra-peritoneal ovarian cancer metastasis." (PMID 35565412, 2022). "Therefore, we used the R package to further analyze the TCGA database and the GEPIA2 database to confirm the high expression of MSLN in ovarian cancer." (PMID 35692779, 2022). "Mesothelin is a 40-kDa cell surface glycoprotein, which is highly expressed in several human cancers, including lung cancer (∼50% of cases) (Ordóñez, 2003), ovarian cancer (∼70% of cases) and pancreatic/biliary adenocarcinomas (∼100% of cases)." (PMID 35795565, 2022). "We confirmed the overexpression of MSLN in the chemoresistant ovarian cancer cell lines." (PMID 35692779, 2022). "Studies of human ovarian cancer have revealed that the cancer antigen CA125 can serve as a ligand of MSLN, and co-expression of MUC16 and MSLN is known to be associated with the invasion process of cancers, with MUC16 promoting the potential role of MSLN in tumor adhesion, and metastasis." (PMID 36358290, 2022). "In our opinion, although many clinical trials regarding MSLN-targeting therapies in ovarian carcinomas are ongoing, further studies will be useful for providing other satisfactory results and for establishing their effects on the health and behavioural outcomes of patients." (PMID 35565412, 2022). "In addition, the high expression of MSLN was significantly correlated with the decreased overall survival at different grades of ovarian cancer (Grade 1, p=0.0099; Grade 2, p=0.038; Grade 3, p=0.0037) (H−J)." (PMID 35692779, 2022).
ovarian carcinoma (continued). "In line with this, we detected low levels of trogocytotic CAR T cells during co-cultures with parental OVCAR-3 and SKOV-3 cells, indicating that M28z and MBBz CAR T cell-mediated trogocytosis can occur in a clinical setting as MSLN expression varies among and within ovarian cancer patients." (PMID 35898704, 2022). "The combination of anti-MSLN and ovarian cancer cells reversed migration and apoptosis." (PMID 33613114, 2021). "In vivo, our data suggest that antibodies targeting mesothelin may offer a therapeutic option for ovarian cancer patients with high levels of serum CA125." (PMID 33613114, 2021). "Our results demonstrated that CA125 via the MSLN/DKK1/SGK3/FOXO3 pathway accelerates cell migration, and targeting mesothelin may potentially be utilized in ovarian cancer therapy." (PMID 33613114, 2021). "In our studies, anti-MSLN was proven to induce apoptosis and necrosis of ovarian cancer cells." (PMID 33613114, 2021). "MSLN is expressed on the surface of mesothelial cells, mesothelioma and ovarian cancer cells." (PMID 33613114, 2021). "Top ranked tumor entities, such as ovarian carcinomas, endometrium carcinomas, pancreatic adenocarcinomas, and malignant mesothelioma, thus, may be the best candidates for therapy with drugs targeting MSLN." (PMID 33917081, 2021). "Mesothelin is a potential therapeutic target for the treatment of ovarian cancer metastasis." (PMID 33613114, 2021). "Mesothelin (Msln) is another frontier antigen for ovarian cancer." (PMID 34386017, 2021). "To recapitulate advanced stage OvCa with peritoneal metastasis and ascites accumulation, we utilized a syngeneic immunocompetent mouse model of advanced-stage ovarian cancer metastasis, to investigate the role of host MSLN expression on ovarian cancer metastasis." (PMID 34830322, 2021). "Notably, all responding patients had at least 60% tumor mesothelin expression (2+ or 3+ by IHC), with 14 patients on treatment for more than 200 days (9 mesothelioma and 5 ovarian cancers)." (PMID 33509252, 2021). "Interestingly, recent studies report that the binding mesothelin to Ca125 plays a crucial role in metastasis creation via spreading ovarian cancer cells in the peritoneal cavity." (PMID 34768993, 2021). "Through in vitro and in vivo studies, we found that MSLN expression contributes to the uniqueness of ovarian cancer dissemination in the peritoneum by promoting cell survival in suspension, invasion through the mesothelial layer and spread within the peritoneal cavity." (PMID 32612258, 2020). "Moreover, mesothelin-targeted IVT CAR lymphocytes significantly inhibited tumor growth in an in vivo humanized murine ovarian cancer model engineered to express human mesothelin." (PMID 32899932, 2020). "In addition, we found that ovarian cancer has the highest MSLN expression among the TCGA cancer types." (PMID 32612258, 2020). "To reinforce the role of MSLN in the peritoneal dissemination process, we compared the peritoneal metastatic potential in nude mice of ovarian cancer cell lines that “naturally” express high levels of MSLN with ovarian cancer cell lines that “naturally” express low levels of MSLN." (PMID 32612258, 2020). "Many (76%) women with ovarian cancer have the targetable 69 kDa cell-bound mesothelin." (PMID 32764223, 2020). "Mesothelin (MSLN) is highly expressed in pancreatic and ovarian cancer." (PMID 33081383, 2020). "To further explore the role of MSLN in the metastatic potential of ovarian cancer cells in vivo, we developed a model using luciferase labeled ovarian cancer cells and IVIS Lumina in vivo imaging as a non-invasive approach to track tumor burden and dissemination over time." (PMID 32612258, 2020). "MSLN is a glycosylphosphatidyl inositol (GPI)-linked protein that is expressed by mesothelial cells lining the peritoneum and highly overexpressed in various types of cancers, such as mesothelioma, ovarian cancer, gastric cancer, and PDA." (PMID 32780245, 2020).
ovarian carcinoma (continued). "In this study, we provide evidence indicating that MSLN is a key player in peritoneal dissemination of ovarian cancer by promoting cell survival in suspension, mediating invasion of cell clusters through the mesothelial layer and spreading to organs within the peritoneal cavity." (PMID 32612258, 2020). "Our aim was to address the essentially unknown role of MSLN in the intraperitoneal dissemination of ovarian cancer." (PMID 32612258, 2020). "Therefore, unveiling the role of MSLN in the malignant progression of ovarian cancer will clarify its possible interest in clinical applications, including prognostic evaluation and therapeutic targeting." (PMID 32612258, 2020). "Mesothelin is expressed in low levels in mesothelial cells of pericardium, pleura and peritoneum of healthy individuals, but is overexpressed in a variety of cancers, including but not limited to stomach, pancreatic, lung, breast and ovarian cancer." (PMID 32751977, 2020). "Studies on ovarian cancer cell lines showed that mesothelin is involved in tumor adhesion and metastasis based on its binding to MUC16 (also known as CA125), due to its rich glycosylation, where O-linked and N-linked MUC-16 oligosaccharides triggered heterotypic cell adhesion." (PMID 33344222, 2020). "It is possible that MSLN overexpression with hydrosalpinx precedes tubal and/or ovarian cancer." (PMID 31222072, 2019). "In addition, MMP-7 also promotes the invasion and metastasis of ovarian cancer through MSLN-activated MAPK/ERK and JNK pathways." (PMID 29393911, 2018). "Mesothelin represents another candidate target for the treatment of ovarian cancer." (PMID 30344925, 2018). "Also, the binding of CA125 to mesothelin, which is expressed by mesothelial cells, mediates ovarian cancer cell adhesion." (PMID 29458390, 2018). "Moreover, mesothelin is highly expressed in various types of cancers, including malignant mesothelioma, ovarian cancer and pancreatic cancer." (PMID 30333914, 2018). "Given the safety confirmation with transient CAR mesothelin expression, a second trial (NCT02159716) was conducted in patients with mesothelioma, ovarian cancer, and pancreatic cancer using a lentiviral transduction vector expressing the same murine-based anti-mesothelin second-generation CAR." (PMID 28862644, 2017). "Thus, Hassan and colleagues previously showed that serum mesothelin is detectable in patients with mesothelioma or in serum, from patients with ovarian cancer at a significantly higher median concentration as compared to serum from healthy donors." (PMID 29113296, 2017). "Accordingly, it has been shown that even mesothelin, the most prominent biomarker for mesothelioma, might be a suitable biomarker to detect ovarian cancer." (PMID 28321148, 2017). "In ovarian cancer, it has been shown that mesothelin binds to ovarian cancer antigen MUC16 (CA-125) and may contribute to dissemination into the abdominal cavity." (PMID 28460459, 2017). "Mesothelin (MSLN) is a cell surface protein highly expressed in several types of malignant tumors, such as malignant mesothelioma, ovarian cancer, pancreatic adenocarcinoma, and lung adenocarcinoma, sometimes in association with increased tumor aggressiveness and poor clinical outcome." (PMID 28460459, 2017). "Moreover, TGF-β1 silencing promoted expression of known ovarian carcinoma antigens as mesothelin and HE4." (PMID 28713366, 2017). "Mesothelin is a membrane-bound glycoprotein expressed by mesothelial cells in the lung pleura, pericardium, and peritoneum of healthy individuals and overexpressed in pancreatic and epithelial ovarian cancers making it a potential immune target." (PMID 25933160, 2015). "As MSLN is highly expressed in various human tumors, our findings suggest that MSLN-specific imaging using 64Cu-labeled 11-25 mAb has the potential to be widely used in the diagnosis of patients with MSLN-positive cancers such as malignant mesotheliomas and ovarian cancers and pancreatic cancers." (PMID 25883990, 2015).